MIR7705 (microRNA 7705)
Synonyms: hsa-mir-7705
Gene: MicroRNA gene on chromosome 8 (100,702,968 to 100,703,024, reverse strand). Ensembl gene ENSG00000284570.
Homologues: Orthologues: chimpanzee MIR7705 (100% identical).